VENTXP1 (VENT homeobox pseudogene 1 )
Synonyms: CT18; NA88A; VENTX2P1
Gene: Long non-coding RNA gene on chromosome X (26,558,247 to 26,881,029, forward strand). Ensembl gene ENSG00000293226.
Diseases named in the same sentence as VENTXP1 in open-access papers:
VENTXP1 is named in the same sentence as 3 diseases in open-access papers, as found by Europe PMC text mining. Sharing a sentence is not in itself a finding about the gene and the disease. The quoted sentences say what the papers report.
head and neck squamous cell carcinoma (2 papers, 2020 to 2022). A squamous cell carcinoma that arises from any of the following anatomic sites: lip and oral cavity, nasal cavity, paranasal sinuses, pharynx, larynx, and salivary glands. "VENTXP1 inhibits tumor growth by suppressing NF-κB signaling in head and neck squamous cell carcinoma." (PMID 35281467, 2022).
tumor (2 papers, 2020 to 2022). "Encouraged by the recapitulation of documented cancer-related lncRNAs, we validated the frequently epigenetically silenced lncRNA, VENTXP1, as a putative tumor suppressor." (PMID 33037177, 2020). "To assess the tumor-suppressing function of VENTXP1 in vivo, we established a xenograft model of HNSCC." (PMID 33037177, 2020). "By further integrating these data with the clinical data and the results from mechanism study, we proposed an oncogenic role of lncRNA VENTXP1 in tumor proliferation and metastasis." (PMID 33037177, 2020). "This positive correlation of VENTXP1 and ANKRD2 expression was further confirmed in HNSCC tumor samples, VENTXP1-overexpressed xenografts, and in HNSCC cell lines." (PMID 33037177, 2020). "Tumor volumes and weights were decreased in mice harboring the VENTXP1-overexpressing tumors." (PMID 33037177, 2020). "The lncRNA VENTXP1 has never been reported to inhibit tumor proliferation in any solid tumor." (PMID 33037177, 2020).
cancer (1 paper, 2020). A tumor composed of atypical neoplastic, often pleomorphic cells that invade other tissues. "We identified that lncRNA VENTXP1 was epigenetically silenced in multiple cancer types, and its lower expression was correlated with poorer survival in HNSCC patients." (PMID 33037177, 2020). "We characterized the DNA methylation landscape of lncRNA genes across four cancer types, and found that methylation of the gene enocoding lncRNA VENTXP1 was recurrently altered in tumors." (PMID 33037177, 2020). "This revealed that only expression of VENTXP1 was significantly lower in carcinoma than in normal tissues." (PMID 33037177, 2020). "In silico analysis indicated that four lncRNAs, LINC00461, LINC00668, VENTXP1, and RP11-81H3.2 were most significantly silenced in both tumors and cancer cell lines." (PMID 33037177, 2020).